ACE (angiotensin I converting enzyme)
Diseases named in the same sentence as ACE in open-access papers (continued):
Sharing a sentence is not in itself a finding about the gene and the disease.
cardiovascular disease (continued). "Another in vitro studies the results showed that A. Bosporus has anti-hypertensive activity due to presence of amino acids and peptides that possess the potential to protect from cardiovascular diseases by inhibiting the activity of ACE." (PMID 40837429, 2025). "In the past few decades, a lot of investigation has been done on medicinal plants for treating cardiovascular diseases, providing insight into natural sources for ACE inhibition." (PMID 39771606, 2024). "Zofenopril, a thiol-containing angiotensin-converting enzyme (ACE) inhibitor, has been identified as a novel H2S donor with significant clinical value in treating cardiovascular diseases." (PMID 39062455, 2024). "Due to this, ACE inhibitors have been widely developed to prevent the production of angiotensin II and the triggering of cardiovascular disease." (PMID 38352804, 2024). "Additionally, drugs (anticoagulants, Beta-Blockers, ACE Inhibitors, Antiplatelet Agents, ARBs, and diuretics) did not have an impact on the incidence of surgical complications, marginal bone loss, peri-implant parameters, or implant survival rate among patients with cardiovascular diseases." (PMID 38398237, 2024). "Important areas for future study are the many other peptides affected by ACE and the many other functions of ACE apart from Ang II production and cardiovascular disease." (PMID 38763333, 2024). "Telmisartan by itself or in combination with other drugs, beta-blockers, calcium channel blockers, diuretics, and ACE inhibitors were more commonly prescribed for the treatment and prophylaxis of cardiovascular diseases in our study." (PMID 38389602, 2024). "Despite the modest benefits observed with normal clinical doses of ACE inhibitors in slowing cardiovascular disease (CVD) end-organ damage, there is growing recognition of the incomplete blockade of RAAS as a contributing factor." (PMID 39046229, 2024). "Secondary preventive measures, like anti-platelet medications, B-blockers, and angiotensin-converting enzyme (ACE) inhibitors, have been found to dramatically lower the risk of cardiovascular disease." (PMID 39329040, 2024). "Maintaining a proper balance between ACE and ACE2 is essential for homeostasis, and imbalances have been linked to various cardiovascular disorders." (PMID 39452857, 2024). "The prescription of ACE inhibitors or angiotensin receptor blockers should be with caution in patients with cardiovascular disease as these medications can upregulate ACE2 and potentially aggravate the patient’s health outcome." (PMID 38957820, 2024). "A meta-analysis evaluating sex differences in cardiovascular medication prescription showed that ACE inhibitors and beta-blockers (only among patients with established cardiovascular disease) were less likely prescribed to women." (PMID 38511098, 2023). "Patients with myocardial injury are often older and have a history of cardiovascular disease, and use ACE inhibitors or angiotensin receptor blockers." (PMID 37600048, 2023). "This group of drugs includes aspirin, statins, beta-blockers, angiotensin II receptor antagonists and angiotensin-converting enzyme (ACE) inhibitors, all of which are used to treat cardiovascular disease." (PMID 38029085, 2023). "The presence of cardiovascular disease and the use of beta blockers or ACE inhibitors are of particular importance when considering performing HV-AIT." (PMID 38143939, 2023). "Chymase, a serine endopeptidase, is highly expressed in the heart of patients with cardiovascular diseases compared to ACE, and reportedly ∼75% of Ang II is estimated to be generated from Ang in cardiac tissues by chymase rather than ACE." (PMID 37404743, 2023). "Cardiovascular disease medications such as aspirin, statins, and blood pressure-lowering drugs including ACE inhibitors have been included in the World Health Organization (WHO) Essential Medicines List (EML) for many years." (PMID 36922850, 2023).
cardiovascular disease (continued). "This fact observed with the ACE inhibitors can also be transferred to other treatments commonly used in HF and cardiovascular disease, such as statins or anticoagulant drugs." (PMID 37510764, 2023). "ACE inhibitors are a class of medicines that are used for the treatment of distinct disorders and are the first-class alternative for cardiovascular disease treatment." (PMID 37389408, 2023). "In contrast, the downregulation of ACE2 expression in patients with cardiovascular disease within cardiac myocytes with the unfavorable effect of an imbalance in the ACE/ACE2 ratio." (PMID 36985188, 2023). "For these reasons, the ACE gene has been a preferred target in unraveling the molecular complex structure of cardiovascular diseases." (PMID 35741131, 2022). "For example, inhibitors of the human protease angiotensin-converting enzyme (ACE) are used in the treatment of cardiovascular disorders." (PMID 35883544, 2022). "The angiotensin converting enzyme (ACE) is a vital enzyme in RAAS, playing a major role in development of cardiovascular diseases with I/D polymorphism of the ACE gene." (PMID 36246876, 2022). "ACE, which is produced by endothelial cells and is a major player in the renin-angiotensin system, plays a significant role in the development of cardiovascular disease by controlling blood pressure and water balance in the body." (PMID 35204069, 2022). "Perindopril is an angiotensin-converting enzyme (ACE) inhibitor that has a crucial role in the management of cardiovascular disorders." (PMID 35631426, 2022). "Given the high global prevalence of cardiovascular disease and the use of ACE inhibitors for first‐line treatment, it is crucial to develop ACE inhibitors with better safety profiles and/or novel mechanisms of action." (PMID 35818993, 2022). "Angiotensin-converting enzyme (ACE) has been a focus of molecular docking studies in relation to cardiovascular diseases to further understand the action of peptides working within its domains." (PMID 35621968, 2022). "The landmark EMPA-REG trial for patients with T2DM demonstrated that EMPA decreased cardiovascular mortality in patients with cardiovascular disease already receiving the standard of care (i.e., ACE inhibitors or ARBs)." (PMID 33806551, 2021). "There is strong evidence that anti‐platelet therapy, ACE inhibitors, beta‐blockers and statins are cost‐effective in reducing subsequent cardiovascular disease (CVD) events in patients with atherosclerotic cardiovascular disease (ACVD)." (PMID 33528881, 2021). "ACE inhibitors and angiotensin II receptor blockers (ARBs) have been used for the treatment of cardiovascular diseases." (PMID 34769508, 2021). "In fact, patients with cardiovascular diseases also receive the treatments with aspirin, β-blockers, ACE inhibitors statins and other drugs at the same time." (PMID 33731005, 2021). "Of note, ACE-Is have an anti-fibrinolytic effect in humans, and recent guidance recommends continuing these drugs in patients with cardiovascular diseases." (PMID 33391014, 2020). "Compound homozygosity (i.e., ACE D/D + PAI-1 4G/4G) for ACE and PAI-1 polymorphisms that have been linked to increased cardiovascular disease and renal disease risk was associated with an increased incidence of macroangiopathic disease in diabetic patients." (PMID 32728402, 2020). "ACE inhibitors and ARBs are among drugs most commonly used worldwide for the treatment of cardiovascular diseases." (PMID 32850989, 2020). "Bioactive peptides with the strongest radical scavenging activity and ACE inhibitory activity would provide a promising solution for the control of cardiovascular diseases." (PMID 32635431, 2020). "Despite evidence for increased expression of ACE2 in patients with cardiovascular disease who are treated with ACE inhibitors (ACE-I) and angiotensin receptor blockers, the actual impact of these drugs on COVID-19 was reported to be controversial." (PMID 33391014, 2020).
cardiovascular disease (continued). "Blockade of RAS with angiotensin-converting enzyme (ACE) inhibitors or AT1 receptor antagonists has been proven to be effective for many cardiovascular diseases." (PMID 32463098, 2020). "Given the positive effects of ACE inhibitors in the prevention and treatment of cardiovascular disease, it seems counterintuitive that ACE expression decreases in endothelial cells activated by inflammatory stimuli." (PMID 31042763, 2019). "ACE (angiotensin-converting enzyme) inhibitors and angiotensin-2 antagonists, normally used to regulate blood pressure and prevent cardiovascular diseases, have been shown to diminish radiation-induced tissue damage in preclinical models." (PMID 31555602, 2019). "ACE inhibitors and ARBs are used in the treatment of cardiovascular diseases with good results, including for RA patients." (PMID 30288187, 2018). "The third paper found that methylation at two out of three CpG sites in ACE (angiotensin-converting enzyme, a gene related to cardiovascular disease) was lower among LBW children (6-12y) compared with normal birth weight children." (PMID 30096154, 2018). "Ac-SDKP is a compelling peptide to treat cardiovascular diseases since its endogenous plasma levels increase with ACE inhibitors." (PMID 29364896, 2018). "All the identified flavonoids of Coriandrum sativum possess the essential structural features required for the activity to regulate the ACE to ultimate control and manage blood pressure and other related cardiovascular diseases." (PMID 30581531, 2018). "Clinical and experimental studies that evaluated heart rate variability after inhibition of ACE in cardiovascular disease also led to an increase in HF oscillations and decrease in both LF oscillations and the LF/HF ratio." (PMID 28386233, 2017). "The adverse effects of the RAS on cardiovascular disease are mainly due to increased AngII, which exerts its effects through the classical ACE-AngII-AT1R axis." (PMID 28212603, 2017). "Albuminuria screening seems not only effective but also cost-effective, when taking possible treatment with angiotensin-converting-enzyme (ACE) inhibitors into account, as it reduces the risk of both CKD and cardiovascular disease." (PMID 27491315, 2017). "Statins, such as simvastatin, and ACE inhibitors (ACEis), such as ramipril, are standard therapies for the prevention and treatment of cardiovascular diseases." (PMID 27590905, 2016). "Angiotensin-converting enzyme (ACE) inhibitor use was significantly higher among intervention group patients with known cardiovascular disease, as was sulphonylurea use among intervention group diabetic patients with BMI ≥ 30 kg/m2." (PMID 27875542, 2016). "Based on those findings it is most probable that the reduced metabolism of bradykinin contributes to the positive properties of the ACE inhibitor in patients suffering from cardiovascular diseases." (PMID 28025602, 2016). "Single nucleotide polymorphisms (SNPs) of RAS genes such as angiotensinogen (AGT), angiotensin-converting enzyme (ACE), and angiotensin II type 1 receptor (AT1R) are known to be associated with cardiovascular diseases." (PMID 25961019, 2015). "Endogenous ACE inhibition is particularly interesting in light of the clinical effectiveness of ACE inhibitor drugs in cardiovascular diseases, as evidenced by several large-scale trials, and as accepted by the published guidelines." (PMID 24691160, 2014). "Our data suggest that circulating ACE activity is regulated in vivo, an effect which is similar to ACE inhibitory medication in cardiovascular disease." (PMID 24691160, 2014). "ACE inhibitors are an important components of a hypothetical polypill proposed to reduce cardiovascular disease by 80%." (PMID 24691203, 2014). "It is well documented that ACE-inhibition and/or anti-AngII-receptor treatment has anti-atherosclerotic effects in experimental models as well as patients with cardiovascular disease." (PMID 25003524, 2014).
cardiovascular disease (continued). "ACE inhibitor drugs are particularly effective in cardiovascular diseases, pinpointing ACE as a major angiontensin I converting enzyme, in vivo." (PMID 24691203, 2014). "In the present study, we decided to evaluate the effect of oral administration of captopril as it is the routine way for the application of ACE inhibitors during the treatment of cardiovascular diseases." (PMID 25045668, 2014). "In our study we found there was very little clinical inertia when it came to prescribing beta blockers and ACE inhibitors, two drug classes which have morbidity and mortality benefit cardiovascular disease prevention." (PMID 24903262, 2014). "The latest therapeutic guidelines have incorporated all these features •••, and ACE inhibitors are considered to be an important component of the polypill proposed as a means of reducing cardiovascular disease by 80%." (PMID 24691160, 2014). "Angiotensin-converting enzyme (ACE) has been implicated in multiple biological system, particularly cardiovascular diseases." (PMID 23469169, 2013). "Captopril represents the lead compound for the class of angiotensin-converting enzyme (ACE) inhibitors to treat cardiovascular diseases." (PMID 24223058, 2013). "Bacteria fermented milk has been shown to produce peptide inhibitors for proteases such as angiotensin converting enzyme (ACE), an enzyme involved in cardiovascular disorders." (PMID 23201642, 2012). "Inhibition of ACE has been shown to improve pathology in cardiovascular disease, whilst ACE2 is cardioprotective in the failing heart." (PMID 22523556, 2012). "In women of reproductive age it is now understood that oestrogen protects against cardiovascular disease due to the inhibitory effects of oestrogen upon mRNA synthesis of ACE." (PMID 23316249, 2012). "➢ Was a cardiovascular disease medication (e.g., beta-blocker, ACE inhibitor) recommended/discussed/prescribed in the past year?" (PMID 21952084, 2011). "The current recommendations for secondary prevention of cardiovascular disease focus on the prescription of anticoagulants, beta blockers, ACE inhibitors/ARB and lipid-lowering agents." (PMID 18973693, 2008). "Consistently, both Ang II receptor 1 blockers (ARBs) and angiotensin converting enzyme (ACE) inhibitors have been reported to increase the number of EPCs in patients with cardiovascular disease." (PMID 20066135, 2008). "While many associations are not consistently noted from study to study, a review of the available studies reveals a modest overall association of clinical cardiovascular disease or SCA with variants in candidate genes, such as APOE, ACE, and NOS3." (PMID 17903303, 2007). "Angiotensin-converting enzyme (ACE) inhibitors have become a cornerstone in the management of patients with cardiovascular disorders." (PMID 16242049, 2005). "Investigating the interplay between ACE and ACE2 would, thus, offer valuable insights into the mechanisms underlying the known symptoms of cardiovascular dysregulation in Covid-19 as well as other cardiovascular diseases." (PMID 40481263, 2025). "Several studies have also shown that protein hydrolysates from pulses possess angiotensin I converting enzyme ANFs inhibitory properties and have bile acid binding properties and may help to prevent cardiovascular disease." (PMID 40363814, 2025). "Together, these findings highlight that while ACE-inhibitory peptides remain the most extensively studied, peptide-based strategies in cardiovascular diseases potentially extend beyond blood pressure regulation to include vascular repair, plaque stabilization, and endothelial modulation." (PMID 41209547, 2025). "Furthermore, the presence of comorbidities such as chronic pulmonary and cardiovascular diseases, as well as polypharmacy (e.g., beta-blockers and ACE inhibitors) negatively affects the severity of symptoms and the response to treatment in case of FIA [3▪▪,4]." (PMID 40699586, 2025).
cardiovascular disease (continued). "Based on the well-known crucial importanceof ACE and vascularinflammation in cardiovascular disease, our results also provide importantnew insights into how resveratrol consumption may lead to cardiovascularbenefits in an organism facing oxidative stress." (PMID 40331971, 2025). "Clinical practice has shown that ARBs or ACE inhibitors yield positive outcomes in the treatment of cardiovascular diseases, although long‐term use may lead to a side effects." (PMID 39247619, 2024). "Conventional therapeutic drugs for cardiovascular diseases include antihypertensive drugs such as diuretics, angiotensin converting enzyme (ACE) inhibitors, beta blockers, blood thinning drugs (to reduce platelet aggregation), cholesterol lowering drugs and/or antiarrhythmic drugs." (PMID 38169375, 2024). "The ability to non-invasively image COL3 directly may provide a tool to investigate the effects of ACE inhibitors in cardiac fibrosis and other cardiovascular diseases." (PMID 39301014, 2024). "Meanwhile, in America, significant advances in evidence-based therapies, such as the use of thrombolysis, coronary artery bypass grafting (CABG), coronary angioplasty and stents, angiotensin-converting-enzyme (ACE) inhibitors, statins, have revolutionized the treatment of cardiovascular disease." (PMID 38100501, 2023). "Overall, our results, together with the previous findings, suggest that the ACE inhibitor Cap inhibits the onset of cardiovascular disease in periodontal patients, and therefore might be helpful for maintaining general health and improving longevity." (PMID 37983238, 2023). "Therefore, angiotensin-converting enzyme (ACE) inhibitors and angiotensin receptor blockers are key therapeutic tools in the management of cardiovascular disease." (PMID 37956047, 2023). "Since ACE inhibitors is widely used for cardiovascular diseases, our findings suggest that clinical use of ACE inhibitors may increase the incidence or the progression of HCC due to their potential roles in enhancing tumor glucose metabolism." (PMID 37215979, 2023). "In a prospective multicenter study investigating the effect of ACE inhibitors and β-blockers, neither the use of these drugs nor the presence of cardiovascular disease was associated with an increased risk of adverse reactions to VIT." (PMID 37854067, 2023). "This dose of captopril was previously shown to abolish approximately 95% of splenic ACE enzymatic activity in mice infected with Histoplasma capsulatum and is 30- to 50-fold higher than the maximum daily captopril dose used in treating cardiovascular disease in humans." (PMID 36608122, 2023). "ACE inhibitors are widely used to treat cardiovascular diseases and promote angiogenesis." (PMID 36759621, 2023). "Neither ACE polymorphism genotype nor a family history of cardiovascular disease were found to influence antibody levels." (PMID 36916970, 2023). "However, older people (45+ years old) have more severe SSRs after being re-stung, which is related to comorbidity, especially the presence of cardiovascular diseases and medication (beta-blockers or ACE inhibitors)." (PMID 35409999, 2022). "Since ACE inhibitors or ARBs are essential drugs for some patients with cardiovascular diseases, individualized therapeutic decision making might be important." (PMID 34769508, 2021). "ACE-inhibitors have been reported as potent therapies in the treatment and management of cardiovascular diseases, which may be part of the possible mechanism by which the extract protect against oxidative-mediated cardiotoxicity." (PMID 34093172, 2021). "On the one hand, it was suggested that ACE or AT1R inhibitors could still be used for SARS-CoV-2 infected patients with cardiovascular diseases." (PMID 33396184, 2020).